MIF (macrophage migration inhibitory factor)
Diseases named in the same sentence as MIF in open-access papers (continued):
Sharing a sentence is not in itself a finding about the gene and the disease.
peritonitis (4 papers, 2010 to 2023). Inflammation of the peritoneum (tissue that lines the abdominal wall and covers most of the organs in the abdomen). "Anti-macrophage MIF antibodies or lysophosphatidylcholine are ineffective if administered more than 8 or 10 h after the induction of peritonitis." (PMID 29780390, 2018). "Excitingly, treatment with anti-MIF antibodies protected mice from lethal peritonitis induced by Escherichia coli or cecal ligation and puncture (CLP)." (PMID 20169062, 2010). "Furthermore, in a rat model of CLP-induced peritonitis, increased levels of MIF in plasma were found at 6, 20, and 30 h after CLP induction." (PMID 38313162, 2023). "Therefore, before inoculating mice with B. pseudomallei, we injected mice with anti-MIF antibodies using a dosing schedule previously found be protective in a mouse model of E. coli or CLP-induced peritonitis." (PMID 20169062, 2010).
pneumonitis (4 papers, 2005 to 2024). An inflammatory process affecting the lung parenchyma. "The mRNAs detected were for cytokines involved in acute inflammation and the fibrosis of pneumonitis: TNF-α/β, IL-6, IFN-β/γ, IL-6, IL-10, IL-1α/β, IL12 and MIF." (PMID 16336675, 2005). "Moreover, we detect biological differences between the two grades of pneumonitis, highlighting the potential value of cytokines such as CXCL-1, CD154, IL-1ra, IL-23, MIF, PAI-1 and IFN-γ as a prognostic marker for developing high grade of lung toxicity." (PMID 33109238, 2020).
polycystic kidney disease (4 papers, 2015 to 2023). A usually autosomal dominant and less frequently autosomal recessive genetic disorder characterized by the presence of numerous cysts in the kidneys leading to end-stage renal failure. "Thus, like MIF, CD74 may protect from experimental kidney interstitial fibrosis but promotes glomerular injury, while MIF (and potentially CD74) also promotes polycystic kidney disease." (PMID 26441987, 2015).
prostate tumors (4 papers, 2005 to 2021). "In the present study, we demonstrate a significant increase in MIF mRNA associated with prostatic tumors compared with matched benign tissue from the same patients, documenting that upregulation of MIF gene expression is a hallmark of prostatic tumorigenesis." (PMID 16000172, 2005). "Western blots showed that NPRA and MIF are detected in the lysates of primary prostate tumors from TRAMP mice of varying ages (18-30 weeks of age) (lanes 1-4) but not in prostates from age-matched WT C57BL/6 mice (18 and 28 weeks of age) (lanes 5-6)." (PMID 21586128, 2011). "Additionally, in prostate neoplasm, MIF factor has been found precisely corresponding with tumor progression and metastasis." (PMID 34157052, 2021). "Prostate tumor cells implanted in mice deficient in atrial natriuretic peptide receptor A (NPRA-KO) failed to grow, and treatment of TRAMP-C1 xenografts with iNPRA reduced tumor burden and MIF expression." (PMID 21586128, 2011). "Lastly, we examined NPRA and MIF expression in primary prostate tumors from TRAMP mice." (PMID 21586128, 2011).
retinal detachment (4 papers, 2017 to 2026). An eye emergency condition which may lead to blindness if left untreated. "Levels of HGF, IL-6, IL-8, IL-16, IFN-gamma, MCP-1, and MIF were significantly higher in all groups of retinal detachment compared to ERM." (PMID 32542038, 2020). "In an animal model of retinal detachment, MIF was identified by a proteomics screen to be the most important cytokine upregulated in retinal detachment." (PMID 31866994, 2019). "Our findings suggest a rationale to develop and trial MIF inhibitors as adjunctive therapeutics for patients with retinal detachment and other retinal diseases." (PMID 29084983, 2017). "Previously, we showed that inhibiting macrophage migration inhibitory factor (MIF)-a pleiotropic cytokine implicated in inflammation and fibrosis- protects the retinal neuron structure and function in a mouse model of retinal detachment and chick model of excitotoxic damage." (PMID 41544460, 2026). "The concentrations of three molecules out of six were higher than 1 ng/ml in all retinal detachment groups (median concentrations in PVR: HGF = 8.135 ng/mL, MCP-1 = 1.950 ng/mL, MIF = 4.371 ng/mL)." (PMID 32542038, 2020). "Levels of HGF (p<0.0001), IFN-gamma (p<0.0001), IL-6 (p<0.0001), IL-16 (p<0.0001), MIF (p<0.0001), MCP-1 (p<0.0001) were significantly higher in all groups of retinal detachment compared to the group of ERM." (PMID 32542038, 2020). "The concentrations of HGF, IFN-gamma, IL-6, IL-16, MIF, MCP-1 were significantly higher in all groups of retinal detachment compared to controls." (PMID 32542038, 2020).
scleroderma (4 papers, 2010 to 2018). Scleroderma is a rare autoimmune connective tissue disorder characterized by abnormal hardening of the skin and, sometimes, other organs. "Since we are interested in the role of MIF in fibrotic diseases, such as scleroderma, we simply added MIF antibody in the conditioned medium of stimulated mast cells." (PMID 25826375, 2015). "On the other hand, MIF was reported to facilitate fibrosis process which represents the substantial pathological changes in scleroderma." (PMID 25826375, 2015). "Serum MIF levels and dermal fibroblast-derived MIF synthesis are both up-regulated in scleroderma, suggesting that MIF participates in the amplifying proinflammatory loop that leads to sclerodermal tissue remodeling." (PMID 22046508, 2010). "In addition, both the circulating levels and the tissue expression of MIF are elevated in patients with autoimmune inflammatory disorders, and high-expression MIF alleles have been associated with more severe end-organ damage in RA, SLE, and scleroderma." (PMID 29915588, 2018). "Based on these existing data, we hypothesized that MIF produced by mast cells may promote fibrosis process in pathogenesis of scleroderma." (PMID 25826375, 2015). "Emerging evidence has shown that MIF is involved in pathophysiology of scleroderma." (PMID 25826375, 2015). "Macrophage Migration Inhibitory Factor is a mast cell released pro-inflammatory cytokine which is deregulated in scleroderma patients and is also involved in non-scleroderma related fibrosis." (PMID 25826375, 2015).
Splenomegaly (4 papers, 2016 to 2026). Abnormal increased size of the spleen. "While MIF expression was increased on days 15 and 16 of CSC, it was decreased in CSC versus SHC mice on day 20 despite persisting splenomegaly, increased CD11b expression and functional GC resistance." (PMID 34675935, 2021). "Collectively, in T. congolense-infected mice, the absence of MIF results in a reduced pro-inflammatory immune response, which in turn could contribute to a lower hepato-splenomegaly and an enhanced B-cell response that collectively could enhance the survival time." (PMID 27632207, 2016).
urinary tract infection (4 papers, 2008 to 2021). "It should be noted that elevated urine levels of MIF were observed in patients with radiation cystitis, urinary tract infections and interstitial cystitis with Hunner lesions." (PMID 34424927, 2021). "Although elevated levels of urinary MIF are found in individuals with urinary tract infections (UTIs), the upregulation of MIF in the context of a UTI has only been found in patents with APN." (PMID 23319831, 2012).
vasculitis (4 papers, 2010 to 2026). "Finally, since there is a known association between thyroid disease and AAV in addition to antithyroid drugs being associated with the development of ANCA and vasculitis, we investigated the role of thyroid hormone activity and MIF in AAV." (PMID 26858715, 2016). "We found that in RV patients, there are significant positive correlations between MIF levels and vasculitis disease activity scores and serum levels of immune complex and a significant negative correlation between MIF levels and serum complement levels." (PMID 22046508, 2010). "ANCA-positive IgGs (obtained from 5 active MPO-ANCA- and 3 active PR3-ANCA-positive vasculitis cases) were used to assess whether ANCA would induce respiratory burst in MIF-treated neutrophils." (PMID 31248381, 2019). "The elevated MIF levels seen in MPA patients correlated positively with indexes of disease activity, including Birmingham vasculitis activity scores, CRP levels and ESR." (PMID 22046508, 2010). "Although there are no data on the capacity of MPO-ANCA to stimulate secretion of any cytokine, including MIF, we would expect it to be related to disease activity and MIF levels, because there appears to be positive relation between MPO-ANCA titers and vasculitis disease activity." (PMID 22046508, 2010). "We also recently observed that serum MIF levels are significantly higher in RA patients with vasculitis (rheumatoid vasculitis; RV) than in those without it (manuscript in preparation)." (PMID 22046508, 2010). "Increased levels of circulating MIF in serum have been found particularly in active AAV patients, but not in patients with other forms of vasculitis, such as giant cell arteritis and polyarteritis nodosa." (PMID 26858715, 2016).
visceral leishmaniasis (4 papers, 2012 to 2023). A severe form of leishmaniasis characterized by irregular bouts of fever, substantial weight loss, swelling of the spleen and liver, and anemia (which may be serious). "In this study, we evaluated a vaccine against visceral leishmaniasis consisting of a double genetically deficient Leishmania donovani for the Centrin 1 gene and macrophage migration inhibitory factor (LdCen−/−MIF−/−)." (PMID 37147351, 2023). "On the other hand, a recent study demonstrated that patients with visceral leishmaniasis caused by L. chagasi have increased plasma concentrations of MIF." (PMID 22496958, 2012). "Another study found that plasma MIF and lipopolysaccharide levels were elevated in patients with American visceral leishmaniasis co-infected with HIV, and corresponded with a weakened T cell response and worsened systemic inflammation." (PMID 32244916, 2020). "Thus, in contrast to the protective role of host MIF demonstrated in mice, MIF production in humans may correlate with worsened inflammation and disease during cutaneous and visceral leishmaniasis." (PMID 32244916, 2020). "Likewise, MIF has been shown to participate in Toxoplasma gondii-induced pathology following oral infection in mice, whereas bloodstream MIF was found to positively correlate with lipopolysaccharide (LPS) plasma levels and chronic immune imbalance in active visceral leishmaniasis patients." (PMID 23451183, 2013). "Patients with visceral leishmaniasis due to infection with L. donovani presented CD4+ lymphocytes expressing low amounts of CD2, IFN-γ, and MIF." (PMID 22496958, 2012).
ZIKV infection (4 papers, 2018 to 2025). "DENV infection in Mφs triggers MIF secretion and hampers migration, whereas ZIKV infection prolongs migration and suppresses proinflammatory responses." (PMID 39537185, 2025). "Conversely, ZIKV infection disrupts the nuclear factor‐kappa B (NF‐κB)‐MIF feedback loop and leads to the inhibition of the NF‐κB signalling, representing a key mechanistic difference of these two viruses." (PMID 39537185, 2025). "ZIKV infection inhibits macrophage migration inhibitory factor (MIF) expression by disrupting the NF-kB-MIF positive feedback loop, resulting in the prolonged migration of infected macrophages." (PMID 38137537, 2023). "Furthermore, besides the exceptions of MIF, IL-8, and SDF-1α, the cytokine/chemokine patterns of our RM were elevated during acute phase of ZIKV infection." (PMID 30359380, 2018).
acute GVHD (3 papers, 2025). "SNPs of MIF are associated with an increased rate of acute GVHD." (PMID 41291248, 2025). "This significant difference was noted on day-30 post-HSCT, before the median day of aGVHD onset, which occurred on day 36 post-HSCT, pointing to MIF’s potential role in the etiology of acute GVHD." (PMID 40421032, 2025). "Frequencies of MIF high-expression -794 CATT7 containing genotypes were increased in patients with grade III-IV acute GVHD (aGVHD) (36.8%) compared with patients that did not develop aGVHD (5.8%) and patients with grade II aGVHD (0%), (p=0.0019, 0.0080 respectively)." (PMID 40421032, 2025). "All these factors are also involved in the pathophysiology of acute GVHD through various mechanisms, including regulating inflammation (NOD2), promoting inflammation (IL-17), inducing proliferation and interferon-γ (IL-23R), and amplifying and prolonging immune responses (MIF)." (PMID 41291248, 2025).
acute lung injury (3 papers, 2016 to 2025). A condition of lung damage that is characterized by bilateral pulmonary infiltrates (pulmonary edema) rich in neutrophils, and in the absence of clinical heart failure. "CD74 is expressed on the cell surface of pulmonary macrophages and contributes to macrophage migration inhibitory factor (MIF)-induced inflammatory response in acute lung injury (ALI)." (PMID 27444250, 2016). "MIF contributes to the pathogenesis of LPS-induced acute lung injury (ALI), and could be a therapeutic target in ALI." (PMID 31248381, 2019).
adenoma (3 papers, 2013 to 2025). A neoplasm arising from the epithelium. "Except for NSE (P = 0.0240) and MIF (P = 0.040), none of the markers were able to discriminate between the control groups (healthy individuals and patients with other diseases) and the adenoma patients in the univariate analysis." (PMID 24107468, 2013).
airway hyperresponsiveness (3 papers, 2022 to 2024). "Conversely, upon MIF deficiency or inhibition, asthmatic features, including eosinophil and neutrophil counts, airway hyperresponsiveness, airway smooth muscle thickness, levels of Th2 cytokines, and IgE titers, were found to be significantly reduced." (PMID 39176391, 2024).
aneurysm (3 papers, 2022 to 2023). Bulging or ballooning in an area of an artery secondary to arterial wall weakening. "In addition, other cytokines such as macrophage migration inhibitory factor (MIF) have been implicated in aneurysm pathogenesis." (PMID 37799778, 2023). "Moreover, based on the small number of patients, of which the majority (70%) had AC aneurysms, further investigations are needed to firmly establish if there are associations between circulating MIF and aneurysm location." (PMID 36712451, 2022). "When comparing the different subgroups, a prominent difference in serum MIF levels was observed for patients stratified according to aneurysm location." (PMID 36712451, 2022). "Our findings in a small cohort of aSAH patients provide first data on differences between systemic, global cerebral and local cerebral MIF levels after aSAH, and their potential relation to aneurysm location and DCI." (PMID 36712451, 2022). "In all, SPP1 and MIF signaling between macrophage and SMC subsets might exert an essential role during aneurysm progress among different species." (PMID 36703732, 2022).
arteriosclerosis (3 papers, 2015 to 2023). A vascular disorder characterized by thickening and hardening of the walls of the arteries. "Arteriosclerosis is the main cause of chronic hypoxia hypoperfusion, while MIF is a key mediator of arteriosclerosis, participating in the entire process of arteriosclerosis by promoting leukocyte recruitment and damaging inflammation." (PMID 37190581, 2023). "In addition to pro-inflammatory cytokines such as TNF-α, IL-1β, IL-6, and MCP-1, chemokines such as macrophage migration inhibitory factor and CXCL12 play an important role in the initiation and the progression of arteriosclerosis." (PMID 36670934, 2022).
autism (3 papers, 2018 to 2025). Persistent deficits in social interaction and communication and interaction as well as a markedly restricted repertoire of activity and interest as well as repetitive patterns of behavior. "Interestingly, a connection between MIF and autism has been reported, whereby higher levels of plasma MIF were correlated with autistic behavior." (PMID 30976114, 2019).
autoimmune myocarditis (3 papers, 2010 to 2025). Autoimmune myocarditis is an autoimmune disease that affects the heart. "MIF also induces chemotaxis in fibroblasts and ECs, and the effects of neutralizing MIF in experimental autoimmune myocarditis indicates that it also stimulates migration T cells." (PMID 22046508, 2010). "Evidence suggests that MIF inhibition could serve as a viable therapeutic strategy for certain inflammatory cardiomyopathies such as CCC, autoimmune myocarditis, and viral myocarditis." (PMID 40092999, 2025).
Autoimmune Thyroiditis (3 papers, 2014 to 2021). "Moreover, the severity of autoimmune thyroid disease has also demonstrated a relationship with MIF gene polymorphisms (rs755622 single nucleotide polymorphism [SNP])." (PMID 34575145, 2021). "In the current study, our data suggested that preoperative serum MIF levels were significantly higher in these two autoimmune thyroiditis groups than those in the control group [15.91 (4.16–31.64) vs. 3.82 (1.55–6.54); p = 0.001]." (PMID 34575145, 2021). "The results of the current study demonstrated that preoperative serum MIF levels were significantly elevated in patients with autoimmune thyroiditis." (PMID 34575145, 2021). "MIF levels were positively correlated with TDS score, operation time, and blood loss in the autoimmune thyroiditis group." (PMID 34575145, 2021). "Preoperative serum MIF levels [15.91 (4.16–31.64) vs. 3.82 (1.55–6.54), p = 0.001] were significantly higher in the autoimmune thyroiditis group than in the goiter group." (PMID 34575145, 2021). "This study aimed to investigate the correlation between preoperative serum migration inhibitory factor (MIF) levels and the difficulty of thyroidectomy in patients with autoimmune thyroiditis." (PMID 34575145, 2021). "In conclusion, preoperative serum MIF level is significantly elevated in patients with autoimmune thyroiditis." (PMID 34575145, 2021). "Preoperative serum MIF levels and surgical difficulty factors in patients with autoimmune thyroiditis and benign nodular goiters." (PMID 34575145, 2021). "Preoperative serum thyroid-stimulating hormone (TSH), TSH receptor antibody, thyroid peroxidase antibodies levels, TDS score, and serum MIF levels were significantly higher in the autoimmune thyroiditis group than those in the goiter group." (PMID 34575145, 2021). "Although previous studies have shown a correlation between serum MIF and autoimmune thyroiditis, the clinical application of MIF in thyroidectomy is still lacking." (PMID 34575145, 2021).
bladder pain syndrome (3 papers, 2017 to 2026). "One scoping review found an increased level of fecal and urinary markers (macrophage migration inhibitory factor (MIF) and fecal glyceraldehyde) in patients with bladder pain syndrome (BPS)." (PMID 41598488, 2026). "MIF and/or HMGB1 are potential novel targets in the treatment of bladder pain independent of inflammation and may represent new approaches to understanding and treatment of painful bladder syndrome/interstitial cystitis." (PMID 29263120, 2017).
brain cancer (3 papers, 2007 to 2017). A primary or metastatic malignant neoplasm affecting the brain. "In this paper, we focus on MIF-dependent signaling in redox regulation and brain cancer progression and discuss recent findings in MIF neurobiology." (PMID 22973314, 2012). "Recent studies have confirmed the overexpression of MIF in different cancer including brain cancer." (PMID 28346397, 2017). "Future studies will show whether available MIF and CD74 receptor inhibitors could be efficiently used in our armamentarium against malignant brain tumors." (PMID 22973314, 2012). "In normal brain tissue no cytoplasmic or nuclear staining was noted for MIF yet brain cancer specimens revealed nuclear localization of MIF." (PMID 17650334, 2007).